ENSG00000280893 (novel transcript)
Gene: Protein-coding gene on chromosome 16 (29,812,261 to 29,820,092, forward strand). Ensembl gene ENSG00000280893.
Genetic constraint (gnomAD): Missense variants: 503 observed, 472.83 expected, observed/expected ratio (o/e) 1.06, 90% interval 0.99 to 1.14. Synonymous variants: 201 observed, 184.24 expected, observed/expected ratio (o/e) 1.09, 90% interval 0.97 to 1.23.